LINC02718 (long independently transcribed non-coding RNA 2718)
Gene: Long non-coding RNA gene on chromosome 11 (23,154,587 to 23,203,161, forward strand). Ensembl gene ENSG00000255418.
Diseases named in the same sentence as LINC02718 in open-access papers:
LINC02718 is named in the same sentence as 2 diseases in open-access papers, as found by Europe PMC text mining. Sharing a sentence is not in itself a finding about the gene and the disease. The quoted sentences say what the papers report.
carcinoma (1 paper, 2023). A malignant tumor arising from epithelial cells. "The expression of LINC02718 was lower in tumor tissues than in para-carcinoma tissues (p < 0.05)." (PMID 37745054, 2023).
LINC02718 also shares sentences with these, for which no sentence is quoted: tumor (1 paper).